SOX7 (SRY-box transcription factor 7)
Diseases named in the same sentence as SOX7 in open-access papers (continued):
Sharing a sentence is not in itself a finding about the gene and the disease.
ovarian carcinoma (2 papers, 2014 to 2023). A malignant neoplasm originating from the surface ovarian epithelium. "Although further studies are needed to elucidate the underlining mechanisms of interactions between SOX7 and the Wnt/β-catenin signaling pathway, our result demonstrates the suppressive function of SOX7 in the carcinogenic process of ovarian cancer." (PMID 25297608, 2014). "One of the members, SOX7, is associated with the development of a variety of cancers as a tumor suppression factor, but its relevance with ovarian cancer was unclear." (PMID 25297608, 2014). "In the greater context of ovarian cancer, SOX7 has been regarded as a tumor suppressor and a potential negative regulator of the Wnt pathway." (PMID 37175530, 2023). "The protein expression of SOX7 in ovarian cancer was quantified by using immunohistochemistry data from the Human Protein Atlas (proteinatlas.org), in which most cases had a “low” or “not detected” expression of SOX7." (PMID 37175530, 2023). "Both kinds of data showed that the expression of SOX7 was significantly reduced in ovarian cancer and the levels of expression were correlated with tumour progression." (PMID 25297608, 2014). "We found that the expression of SOX7 was reduced significantly in ovarian cancer tissues compared with normal controls (ovarian cancer mean: 3.50 vs. normal peritoneum mean: 53.96, FDR =7.4e-07)." (PMID 25297608, 2014). "Our results obtained from different platforms indicate that the expression levels of SOX7 were significantly reduced in all types of ovarian cancers studied here, though at different extents." (PMID 25297608, 2014). "In this study, we chose ovarian cancer to work on primarily due to the fact that this disease is so devastating in females and that to date relatively little has been done on SOX7 in ovarian cancer." (PMID 25297608, 2014). "Based on the findings in this study, we propose that SOX7 is a key factor during ovarian cancer progression and is a useful prognostic marker." (PMID 25297608, 2014). "To investigate the correlation between SOX7 and the state of ovarian cancer, we compared the SOX7 gene expression profiles of forty-three serous ovarian cancers and ten peritoneum controls in GSE12470, with the false discovery rate (FDR) being controlled." (PMID 25297608, 2014). "In this study, we investigated the changes and possible roles of SOX7 in ovarian cancer using the microarray gene expression techniques and validated the results with clinical tissues." (PMID 25297608, 2014). "In this study, we investigated the involvement of SOX7 in the progression and prognosis of epithelial ovarian cancer (EOC) and the involved mechanisms." (PMID 25297608, 2014). "As highly malignant cells are believed to arise from ovarian carcinoma of low malignancy, the expression value of SOX7 should be different among tissues of different malignancy." (PMID 25297608, 2014). "Our results also revealed SOX7 as a negative regulator in the Wnt/β-catenin signaling pathway in ovarian cancer." (PMID 25297608, 2014). "To investigate the mechanism by which SOX7 is involved in the oncogenesis and progression of ovarian cancers, we analyzed genes that were co-expressed with SOX7 and short-listed 7933 genes by Pearson correlation (FDR < 0.01) in GSE27651." (PMID 25297608, 2014). "The expression of SOX7 correlates with tumor progression as a tumor suppressor, possibly through the Wnt/β-catenin signaling pathway in ovarian cancers, suggesting that SOX7 may be a promising prognostic marker." (PMID 25297608, 2014). "To date, nevertheless, the contributions and molecular mechanisms of SOX7 in ovarian cancer are largely unknown." (PMID 25297608, 2014). "Our work reported here suggests, for the first time, that SOX7 may play an important role as a tumor suppressor in ovarian cancer progression." (PMID 25297608, 2014).
ovarian carcinoma (continued). "As SOX7 has been reported to block the transcription of Wnt/β-catenin signaling pathway in various cancers, we postulated that it might have the same function in ovarian cancer." (PMID 25297608, 2014). "The expression of SOX7 was significantly reduced in ovarian cancer tissues compared with normal controls, strongly indicating that SOX7 might be a negative regulator in the Wnt/β-catenin pathway in ovarian cancer." (PMID 25297608, 2014). "A minority of the ovarian cancer tissue sections had positive SOX7 staining intensity, but negative or weak SOX7 staining intensity was seen in most of the malignant ovarian tissues (23/31)." (PMID 25297608, 2014). "Our results demonstrated that the expression levels of SOX7 and its targets, COX-2 and cyclin D1, have an inverse relationship, further supporting our hypothesis that SOX7 is a negative regulator in the Wnt/β-catenin signaling pathway in ovarian cancer." (PMID 25297608, 2014).
squamous carcinomas (2 papers, 2013 to 2025). "Expression level of SOX7 in NSCLC samples was correlated with their histology, with levels being lower in adenocarcinomas compared with adenosquamous and squamous carcinomas." (PMID 23557216, 2013).
Stroke (2 papers, 2012 to 2014). Sudden impairment of blood flow to a part of the brain due to occlusion or rupture of an artery to the brain. "On the other hand, the SOX7 gene, which has not previously been associated with stroke, was highly upregulated at both 24 h and 3 d after ischemia in the core and PI areas and recent data suggest it has a role in vascular development." (PMID 23284893, 2012). "This would make it interesting to analyze the exact role of SOX7 in post-stroke angiogenesis." (PMID 23284893, 2012).
adenosquamous carcinoma (1 paper, 2013). A carcinoma composed of malignant glandular cells and malignant squamous cells. "Expression levels of SOX7 mRNA were correlated with histology (adenocarcinoma had lower expression than either squamous or adenosquamous carcinoma, p= 0.0222) and tumor differentiation (poorly differentiated had lowest expression, p= 0.0607)." (PMID 23557216, 2013).
atherosclerosis (1 paper, 2022). A disease characterized by the build-up of fatty material and calcium deposition in the arterial wall resulting in partial or complete occlusion of the arterial lumen. "Three transcriptional regulators such as RXRA, SOX7, and FOXA2, that have been predicted to bind with SNP rs3136441 in the presence of allele C, may have the pathogenetic role for atherosclerosis." (PMID 35203469, 2022).
atrioventricular septal defect (1 paper, 2021). "We identified a de novo 8p23.1 deletion with Sox7 haploinsufficiency in an atrioventricular septal defect (AVSD) patient using whole exome sequencing in 100 AVSD patients." (PMID 33846290, 2021).
diaphragmatic hernia (1 paper, 2016). A congenital or acquired weakness or opening in the diaphragm which allows abdominal contents to protrude into the chest cavity; congenital diaphragmatic hernias are caused when the embryonic diaphragm fails to fuse. "Its deletion is linked to diaphragmatic hernia, cardiac oedema and apparent lack of yolk sac vasculature, but further characterization of SOX7-deficient embryos will be required to fully understand the main function of SOX7 during embryonic development." (PMID 27411892, 2016).
endometrioid ovarian cancer (1 paper, 2012). "Importantly, we demonstrated that Sox7 inhibited Wnt/β-catenin signaling in endometrial or endometrioid ovarian cancer cells (OEA) harboring not only wild-type but also mutant β-catenin." (PMID 23295859, 2012). "Functionally, enforced expression of Sox7 could significantly inhibit endometrial or endometrioid ovarian cancer cells (OEA) harboring either wild-type or mutant β-catenin." (PMID 23295859, 2012).
endothelial dysfunction (1 paper, 2024). In vascular diseases, endothelial dysfunction is a systemic pathological state of the endothelium (the inner lining of blood vessels) and can be broadly defined as an imbalance between vasodilating and vasoconstricting substances produced by (or acting on) the endothelium. "miR-484 might influence SOX7 expression or activity, and SOX7 might influence the SPARC expression or activity, thereby affecting the downstream pathways involved in endothelial dysfunction and VC." (PMID 39596822, 2024).
epilepsy (1 paper, 2024). A brain disorder characterized by episodes of abnormally increased neuronal discharge resulting in transient episodes of sensory or motor neurological dysfunction, or psychic dysfunction. "The discovery of Y‐box 7 (SOX7), a sex‐determining region in epilepsy's hippocampal neurons, revealed its ability to suppress cell death." (PMID 38676299, 2024). "A signal network involving circUBQLN1/miR‐155/SOX7 helped shed light on epilepsy's pathological mechanism." (PMID 38676299, 2024). "Silence of SOX7 also prevented inhibition of Mg2+‐free induced epilepsy by miR‐155 inhibitors and circUBQLN1 overexpression." (PMID 38676299, 2024). "Validation of the circUBQLN1/miR‐155/SOX7 axis was conducted in epilepsy." (PMID 38676299, 2024).
glaucoma (1 paper, 2023). Increased pressure in the eyeball due to obstruction of the outflow of aqueous humor. "Within Geno2MP, SOX7 A379V was found in six affected individuals, with four having abnormal eye phenotypes (glaucoma or retinal degeneration)." (PMID 36672963, 2023).
leukemia (1 paper, 2017). A malignant (clonal) hematologic disorder, involving hematopoietic stem cells and characterized by the presence of primitive or atypical myeloid or lymphoid cells in the bone marrow and the blood. "Using human leukemia model systems, we establish that the down-regulation of SOX7 in BCP-ALL causes a significant decrease in proliferation and clonogenicity in vitro that correlates with a delay in leukemia initiation and burden in vivo." (PMID 29029405, 2017). "To determine whether SOX7 expression was associated with hematological malignancies, we interrogated the Oncomine database for differential SOX7 expression in leukemias." (PMID 29029405, 2017). "The down-regulation of SOX7 by either shRNAs resulted in a significant decrease in colony formation in both leukemia lines, with much smaller colonies formed upon SOX7 knock-down." (PMID 29029405, 2017). "Our study suggests that SOX7 expression in BCP-ALL is an important factor contributing to leukemia." (PMID 29029405, 2017).
lung squamous cell carcinoma (1 paper, 2023). "SOX13 accounted for 22% of the high-risk variants in lung squamous cell carcinoma, SOX 2 for 33% of pancreas ductal carcinoma, and SOX7 for 40% of thyroid NS cancer." (PMID 36672963, 2023).
lymph node metastasis (1 paper, 2024). "Strikingly, several studies illustrated that low expression of SOX7 in LUAD tissues was related to lymph node metastasis and low OS rate of LUAD patients." (PMID 39346732, 2024). "Previous researches reported that SOX7 was low expression in NSCLC tissues, which was related to lymph node metastasis and low OS rate of LUAD patients." (PMID 39346732, 2024).
malaria (1 paper, 2025). Malaria is a serious and sometimes fatal disease caused by a parasite that commonly infects a certain type of mosquito which feeds on humans. "As for SOX7, significantly enriched pathways are complementary and coagulation cascades, graft-versus-host reaction, and malaria." (PMID 40230854, 2025).
oral cancer (1 paper, 2025). "Previous studies have shown that IL-17F suppresses VM in oral tongue squamous cell carcinoma; HIF-1α/EphA2/Laminin-5γ2 axis downregulation inhibits hypoxia-induced VM in oral cancer; SOX7 inhibits VM by downregulating VE-cadherin in OSCC." (PMID 41502523, 2025).
osteosarcoma (1 paper, 2022). A usually aggressive malignant bone-forming mesenchymal neoplasm, predominantly affecting adolescents and young adults. "lncRNA DARS-AS1 promotes the progression of osteosarcoma by regulating miR-532-3p/CCR7; lncRNA BACE1-AS regulates the proliferation, migration, and invasion of osteosarcoma cells through the miR-762/SOX7 axis; lncRNA SNHG1 promotes osteosarcoma progression by upregulating S100A6 through miR-493-5p." (PMID 36388161, 2022).
plasma cell leukemia (1 paper, 2025). An aggressive plasma cell neoplasm characterized by the presence of neoplastic plasma cells in the peripheral blood. "Here, we evaluated the genetic and epigenetic aberrancies of SOX7 in diagnostic or relapsed MM as well as smoldering MM (SMM) and plasma cell leukemia (PCL)." (PMID 40699642, 2025).
plasma cell neoplasm (1 paper, 2025). A clonal proliferation of immunoglobulin-secreting plasma cells. "Future research will reveal whether SOX7 inactivation has a role in development of these plasma cell neoplasms." (PMID 40699642, 2025).
prostate (1 paper, 2012). "The expression levels of SOX7 (IRS: PCa = 4.01 ± 0.160 vs. Benign = 4.79 ± 0.279, p = 0.024) and SOX10 (IRS: PCa = 2.76 ± 0.174 vs. Benign = 4.00 ± 0.424, p = 0.010) in PCa tissues were lower than those in adjacent benign prostate tissues significantly." (PMID 22703285, 2012).
psoriasis (1 paper, 2022). An autoimmune condition characterized by red, well-delineated plaques with silvery scales that are usually on the extensor surfaces and scalp. "We found that psoriasis and AD share many DEGs and pathways, but also identified regulators, such as FOXE1, FOXM1, STAT3 and SOX7, and discovered a gene regulatory network unique for psoriasis." (PMID 35874668, 2022).
sarcoma (1 paper, 2021). A usually aggressive malignant neoplasm of the soft tissue or bone. "Increased expression of SOX7 and SOX9, as well as cooperation between SOX7 and SOX4, are involved in the process in which upregulation of slug by SOX4, β-catenin/p300 complexes induces EMT and related CSC properties, which in turn promote homologous and heterologous sarcoma components in UCS." (PMID 34881182, 2021).
serous cystadenocarcinoma (1 paper, 2014). A malignant serous cystic neoplasm usually involving the ovary or the pancreas. "In comparison between the protein expression levels of SOX7 with pathological features of the cancer, we found that SOX7 was down-regulated mainly in serous cystadenocarcinoma and advanced stages of the cancers." (PMID 25297608, 2014).
Splenomegaly (1 paper, 2016). Abnormal increased size of the spleen. "Together, these data reveal that Sox7-enforced expression in vivo impairs B lymphopoiesis and expands the haematopoietic progenitor compartment, resulting in splenomegaly and extra-medullary haematopoiesis." (PMID 27411892, 2016).
temporal lobe epilepsy (1 paper, 2020). A localization-related (focal) form of epilepsy characterized by recurrent seizures that arise from foci within the temporal lobe, most commonly from its mesial aspect. "While our research was conducted, it was reported that miR-21-5p regulates SOX7 expression in a rat temporal lobe epilepsy model." (PMID 33203802, 2020).
teratoma (1 paper, 2019). A non-seminomatous germ cell tumor characterized by the presence of various tissues which correspond to the different germinal layers (endoderm, mesoderm, and ectoderm). "The transcriptional analysis of teratoma tissues also showed the expression of genes of all three germ layers: the endoderm (SOX7, and SOX17), mesoderm (BRACHYURY, and MIXL1), and ectoderm (PAX6, and TUJ1)." (PMID 31888235, 2019).
tumor (57 papers, 2009 to 2025). "Publicly available datasets were reanalyzed to evaluate SOX7 copy number, promoter methylation, transcript levels in MM or related neoplasms and to evaluate mutation rates in MM cases." (PMID 40699642, 2025). "Integrative analyses of patient-matched diagnostic and relapsed MM tumor tissues revealed moderate positive correlations between SOX7 copy numbers." (PMID 40699642, 2025). "In this study, we investigated the copy number status and promoter methylation levels of SOX7 in diagnostic or relapsed MM in addition to related neoplasms through different approaches with generally consistent results." (PMID 40699642, 2025). "SOX7 promoter was methylated in 6 of 20 (30%) of the diagnostic MM cases, and 13 of 20 (65%) of the MM tumor samples obtained at relapse." (PMID 40699642, 2025). "In HCC, SOX7 is significantly down-regulated relative to adjacent non-tumor tissue and is associated with the advanced stage of HCC." (PMID 35267473, 2022). "Regarding the mechanisms underlying SOX7-mediated tumor suppression, it was only proposed that SOX7, like several other SOX proteins, interacts with β-catenin to promote its depletion and inhibit its mediated transcription." (PMID 29757932, 2018). "The tumour suppressive role of SOX7 in AML was directly linked to the inactivation of the Wnt/β catenin pathway." (PMID 27411892, 2016). "Clinicopathological correlation revealed that the down-regulated Sox7 was significantly associated with high-grade tumor (P = 0.021) and high level of β-catenin (P = 0.038)." (PMID 23295859, 2012). "Immunohistochemical and quantitative RT-PCR analyses showed that Sox7 was underexpressed and was associated with high-grade tumor (P=0.021), increased expressions of β-catenin (P=0.038) and its downstream targets; CyclinD1 (P<0.001) and FGF9 (P<0.001)." (PMID 23295859, 2012). "On the other hand, the underexpressed Sox7, in contrast to β-catenin, was also associated with high-grade tumor." (PMID 23295859, 2012). "We found that the expression levels of all components of the SHP2-ASK1-c-Jun-SOX7 signaling axis were upregulated or activated in tumor-associated endothelial cells, highlighting the importance of this signaling axis in controlling tumor angiogenesis and vessel abnormality." (PMID 34728626, 2021). "As a transcription factor, SOX7 was reported to transcriptionally regulate several genes related to its tumor suppressor functions in breast cancer cells." (PMID 40699642, 2025). "SOX7 is one of the tumor suppressor candidates located in 8p23.1, a recurrently deleted region in MM." (PMID 40699642, 2025). "The analysis of LARS2, SEZ6L2, and SOX7 in the COAD tumor microenvironment suggests that these genes play significant roles in regulating CD8+ T cell infiltration and function." (PMID 40230854, 2025). "We observed significant downregulation of SOX7 expression in MM bone marrow tumor samples compared to normal bone marrow PC samples when expression levels of RPL37A or EMC7 housekeeping gene were used to obtain normalized expression of each sample." (PMID 40699642, 2025). "In tumor samples obtained at the relapse stage, 3 of 11 (27.3%) cases showed the presence of SOX7 deletions in MM cases." (PMID 40699642, 2025). "Among these three tumor suppressor gene candidates in del8p23.1, a higher number of research articles supported the role of SOX7 as a tumor suppressor in a variety of cancer types compared to other tumor suppressor candidates." (PMID 40699642, 2025). "Next, we evaluated SOX7 deletion status in MM tumor samples obtained during the diagnosis or relapse stage." (PMID 40699642, 2025). "In contrast, endothelial cells can also exert pro‐tumour activity; for example, vascular endothelial cells can regulate SOX7 expression through the ASK1‐c‐Jun signalling pathway, thereby promoting angiogenesis and tumour growth." (PMID 37882107, 2024).